MAL-AS1 (MAL antisense RNA 1)
Synonyms: AC103563.8
Gene: Long non-coding RNA gene on chromosome 2 (95,000,041 to 95,026,757, reverse strand). Ensembl gene ENSG00000233850.
Diseases named in the same sentence as MAL-AS1 in open-access papers:
MAL-AS1 is named in the same sentence as 1 disease in open-access papers, as found by Europe PMC text mining. Sharing a sentence is not in itself a finding about the gene and the disease.
MAL-AS1 shares sentences with these, for which no sentence is quoted: infection (1 paper).